ABL1 (ABL proto-oncogene 1, non-receptor tyrosine kinase)
Diseases named in the same sentence as ABL1 in open-access papers (continued):
Sharing a sentence is not in itself a finding about the gene and the disease.
myeloproliferative neoplasm (continued). "There is consensus between the classifications for BCR::ABL1-negative myeloproliferative neoplasms (MPNs) other than polycythaemia vera (PV)." (PMID 40949653, 2024). "BCR::ABL1‐negative myeloproliferative neoplasms (MPNs) are clonal haematopoietic stem cell disorders characterized by specific driver mutations and an increased risk of both macrothrombosis and microthrombosis." (PMID 39183370, 2024). "Predicting the likelihood vascular events in patients with BCR/ABL1-negative myeloproliferative neoplasms (MPN) is essential for the treatment of the disease." (PMID 38776019, 2024). "BCR::ABL1-negative myeloproliferative neoplasms are hematopoietic disorders characterized by panmyelosis." (PMID 38654055, 2024). "BCR::ABL1-negative myeloproliferative neoplasms (MPNs) are clonal disorders originating from a single haematopoietic stem cell, mainly referred to as polycythaemia vera (PV), essential thrombocythaemia (ET) and primary myelofibrosis (PMF)." (PMID 38771542, 2024). "Typical BCR::ABL1-negative myeloproliferative neoplasms (MPN) are mainly referred to as polycythemia vera (PV), essential thrombocythemia (ET), and primary myelofbrosis (PMF)." (PMID 38771542, 2024). "Over the past decade, tremendous progress has been made in understanding the pathogenesis of BCR::ABL1-negative myeloproliferative neoplasms." (PMID 37745842, 2023). "In the 2008 WHO classification, myeloproliferative disorders initially called ‘Chronic MyeloProliferative Diseases’ (CMPD) were reclassified as ‘MyeloProliferative Neoplasms’ (MPN) with nine entities and were split into BCR::ABL1-positive MPN (CML) and BCR::ABL1-negative MPN." (PMID 36980287, 2023). "This review focuses on how the use of new technologies like next-generation sequencing (NGS) helps in the diagnosis of BCR::ABL1-negative myeloproliferative neoplasms." (PMID 37745842, 2023). "On account of the clinical picture and absence of a BCR::ABL1 fusion, she was diagnosed with a Philadelphia-negative myeloproliferative neoplasm and treated accordingly with hydroxycarbamide." (PMID 37496024, 2023). "The classical BCR::ABL1-negative myeloproliferative neoplasms (MPNs) are hematopoietic stem cell disorders with the clonal proliferation of one or more types of cells of the myeloid lineage." (PMID 37745842, 2023). "Chronic neutrophilic leukemia (CNL) is a rare but potentially aggressive BCR::ABL1 negative myeloproliferative neoplasm, characterized by sustained mature, neutrophilic leukocytosis." (PMID 36568246, 2022). "BCR::ABL1-negative myeloproliferative neoplasms (MPNs) are a group of stem cell disorders characterized by aberrant hematopoietic proliferation with an increased risk of leukemic transformation." (PMID 36611899, 2022). "BCR::ABL1-negative myeloproliferative neoplasms (MPN) comprise a heterogeneous group of hematological neoplastic diseases that is characterized by cytosis of one or more cell lineages in the peripheral blood, associated with a significant risk of developing a secondary acute myeloid leukemia (sAML)." (PMID 40764668, 2025). "PV is a subtype of BCR/ABL1-negative myeloproliferative neoplasms (MPNs)." (PMID 40493419, 2025). "We report a case of extramedullary involvement and leukemic transformation in myeloproliferative neoplasm (MPN), where ETV6::ABL1 was initially overlooked but later detected in the blast phase." (PMID 39066837, 2024). "Chronic myeloid leukemia (CML) is a myeloproliferative neoplasm characterized by bone marrow expansion and the proliferation of one or more myeloid cell lineages, predominantly driven by the expression of the constitutively active fusion product tyrosine kinase BCR:ABL1." (PMID 39051413, 2024). "BCR::ABL1-negative myeloproliferative neoplasms (MPNs) are a group of hematopoietic malignancies in which somatic mutations are acquired in hematopoietic stem/progenitor cells, resulting in an abnormal increase in blood cells in peripheral blood and fibrosis in bone marrow." (PMID 37629188, 2023).
myeloproliferative neoplasm (continued). "The classical BCR::ABL1-negative myeloproliferative neoplasms such as polycythemia vera (PV), essential thrombocythemia (ET), and myelofibrosis (MF) are clonal diseases with the presence of characteristic “driver mutations” in one of the genes: JAK2, CALR, or MPL." (PMID 37745842, 2023). "BCR::ABL1-negative myeloproliferative neoplasms (MPNs) include three major subgroups—polycythemia vera (PV), essential thrombocythemia (ET), and primary myelofibrosis (PMF)—which are characterized by aberrant hematopoietic proliferation with an increased risk of leukemic transformation." (PMID 36611899, 2022). "The annual incidence of BCR-/ABL1-negative myeloproliferative neoplasms (MPN), namely polycythemia vera (PV), essential thrombocythemia (ET), and primary myelofibrosis (PMF) in the western world, is estimated to be maximum 2.8, 2.3, and 1.5 cases per 100.000 population, respectively." (PMID 31781224, 2019). "In addition to MLN-eo-TK, JAK2 rearrangements can also be found in BCR::ABL1-negative myeloproliferative neoplasms (MPN), myelodysplastic neoplasms (MDS), MDS/MPN overlap syndromes, B/T lymphomas, acute myeloid (AML), lymphoblastic (ALL) or mixed- phenotype acute leukemia (MPAL)." (PMID 41530508, 2026). "The classical BCR::ABL1-negative myeloproliferative neoplasms (MPN) include the subtypes essential thrombocythemia (ET), polycythemia vera (PV), and primary myelofibrosis (PMF)." (PMID 38602559, 2024). "The classical BCR::ABL1-negative myeloproliferative neoplasms (MPN) form a group of bone marrow (BM) diseases with the potential to progress to acute myeloid leukemia or develop marrow fibrosis and subsequent BM failure." (PMID 38602559, 2024). "The search yielded nine cases of coexistent MPN and LPD out of a total of 269 patients diagnosed with BCR-/ABL1-negative MPN or an MDS/MPN (myelodysplastic syndrome/myeloproliferative neoplasms) and 1062 patients diagnosed with an LPD." (PMID 31781224, 2019). "According to the 2022 World Health Organization (WHO) classification for hematopoietic malignancies, major categories of BCR::ABL1-negative myeloproliferative neoplasms (MPN) include polycythaemia vera (PV), essential thrombocythaemia (ET), and primary myelofibrosis (PMF)." (PMID 40287867, 2025). "Essential thrombocythemia proved to be the most frequent myeloproliferative neoplasm, which are findings that align with the premises established by Torres15, who studied a population with BCR::ABL1-negative myeloproliferative neoplasms in the state of Amazonas (Brazil)." (PMID 38654055, 2024).
acute myeloid leukemia (84 papers, 2007 to 2026). Acute myeloid leukemia (AML) is a group of neoplasms arising from precursor cells committed to the myeloid cell-line differentiation. "We recently reported a de novo acute myeloid leukemia (AML) patient harboring both BCR::ABL1 p190 isoform and RUNX1::MECOM fusion, a rare and high-risk molecular profile." (PMID 41245943, 2025). "Acute myeloid leukemia (AML) with BCR::ABL1 fusion is a rare but high-risk entity characterized by aggressive disease progression and poor response to conventional therapies." (PMID 41245943, 2025). "Evaluation of pre-HSCT BAALC/ABL1 copy numbers in peripheral blood by ddPCR represents a feasible and rapid way to identify acute myeloid leukemia patients at high risk of early relapse after HSCT." (PMID 29152132, 2017). "These sites include NKX3-1 (8p21.2) and ABL1 (9q34.11-12) genes that are also known to be associated with prostate tumor suppressor gene and translocation mutation relatively in acute nonlymphocytic leukemia." (PMID 20409316, 2010). "We report a 65-year-old man with FLT3 D835V-mutated acute myeloid leukemia (AML) and BCR::ABL1-positive chronic myeloid leukemia (CML) that coexisted as genetically independent clones." (PMID 41982787, 2026). "Patient 2 (P2) F/67Y was an acute myeloid leukaemia (AML) patient with BCR::ABL1 (e19a2) fusion transcript." (PMID 38493200, 2024). "Univariable analyses of overall survival, relapse, and non‐relapse mortality rates after 3 years in acute myeloid leukemia (AML) with BCR::ABL1 group." (PMID 38633128, 2024). "BCR::ABL1 fusion is found in < 1% of de novo acute myeloid leukemia (AML) cases and confers a poor prognosis." (PMID 38633128, 2024). "Acute myeloid leukaemia with BCR::ABL1 fusion is a defined genetic entity in the fifth World Health Organization classification." (PMID 38550948, 2023). "Current guidelines recommend that Acute Myeloid Leukemia (AML) patients with NPM1 mutations should be monitored for measurable residual disease by quantifying the transcripts and normalizing them to ABL1 transcripts." (PMID 36467801, 2022). "For comparison, we present here a patient with BCR::ABL1‐positive acute myeloid leukemia (AML)." (PMID 39932124, 2025). "In the future, prospective studies should evaluate whether acute myeloid leukemia patients with high pre-HSCT BAALC/ABL1 copy numbers benefit from additional treatment before or early intervention after HSCT." (PMID 29152132, 2017). "Acute myeloid leukemia (AML) with BCR::ABL1 fusion occurs only in < 1% of de novo patients with AML." (PMID 38633128, 2024). "Acute myeloid leukemia (AML) with BCR::ABL1 has recently been recognized as a distinct subtype in international classifications." (PMID 37895120, 2023). "When screening our databases for patients for this study, we also identified patients who had history of CML and later developed de novo myelodysplastic syndrome (MDS) or acute myeloid leukemia (AML), with low BCR::ABL1 levels (<1% IS)." (PMID 36307398, 2022). "Using GAB2 deficient mice, we previously showed that GAB2 serves as an important effector of the oncogenic FLT3-ITD receptor tyrosine kinase in acute myeloid leukemia (AML) and of BCR::ABL1 in CML." (PMID 37161070, 2023). "TF1 (human erythroleukemia), HEL (human erythroid leukemia), and F36P (MDS-RAEB) showed varying levels of PTBP2 expression, whereas HNT34 (BCR::ABL1+ human Acute Myeloid Leukemia) cells showed almost no PTBP2 expression among the four AML cell lines." (PMID 40113750, 2025). "Overall findings were consistent with Acute Myeloid Leukemia with monocytic differentiation with features favoring evolvement on top of CML (blast phase), but another differential diagnosis of de novo AML with BCR/ABL1 could not be excluded entirely during diagnostic workup." (PMID 37234472, 2023).
essential thrombocythemia (75 papers, 2012 to 2026). A chronic myeloproliferative neoplasm that involves primarily the megakaryocytic lineage. "The latest World Health Organization (WHO) classified MPNs into chronic myeloid leukemia (CML) BCR::ABL1+, polycythemia vera (PV), essential thrombocythemia (ET), and primary myelofibrosis (PMF)." (PMID 36873934, 2023). "The somatic mutation JAK2-V617F is frequently observed in BCR/ABL1-negative myeloproliferative neoplasms (MPNs): 92% in polycythemia vera (PV), 55% in essential thrombocythemia (ET), and 50% in primary myelofibrosis (PMF)." (PMID 29928488, 2018). "Genetic testing identified a somatic JAK2 V617F mutation (allelic frequency of 17%), consistent with essential thrombocythemia; no other mutations were detected, including no detectable BCR::ABL1 gene." (PMID 41552126, 2025). "The classic BCR::ABL1-negative MPNs, polycythemia vera (PV), essential thrombocythemia (ET), and primary myelofibrosis (PMF), share an overactive JAK2-signaling as a common characteristic with the key driver genes JAK2, CALR, and MPL." (PMID 38835969, 2024). "BCR::ABL1-negative myeloproliferative neoplasms (MPNs) include essential thrombocythemia (ET), polycythemia vera (PV) and primary myelofibrosis (PMF)." (PMID 37002477, 2023). "Myeloproliferative neoplasms, namely the BCR::ABL1-negative subtypes such as polycythemia vera (PV), essential thrombocythemia (ET), and primary myelofibrosis (PMF), are identified as clonal hematopoietic stem cell conditions marked by the aberrant proliferation of myeloid lineages." (PMID 41239536, 2025). "BCR::ABL1-negative MPNs include three major subgroups: polycythemia vera (PV), essential thrombocythemia (ET), and primary myelofibrosis (PMF)." (PMID 36611899, 2022). "This chapter focuses primarily on the classical BCR::ABL1-negative MPN, namely polycythaemia vera (PV), essential thrombocythemia (ET), and primary myelofibrosis (PMF)." (PMID 38835971, 2024). "Polycythemia vera (PV), essential thrombocythemia (ET), and primary myelofibrosis (MF) are the most common BCR::ABL1-negative MPNs, though differ in signs, symptoms, hematological and clinical alterations, and genetic findings." (PMID 38654055, 2024). "Primary myelofibrosis (PMF) is a subtype of BCR::ABL1-negative classic MPN, which also includes polycythemia vera (PV) and essential thrombocythemia (ET)." (PMID 38339265, 2024). "A somatic mutation of JAK2, coding for constitutively activated Jak2-V617F, is frequently observed in BCR/ABL1-negative myeloproliferative neoplasms (MPNs): 96% in polycythemia vera (PV), 55% in essential thrombocythemia (ET), and 65% in primary myelofibrosis (PMF)." (PMID 24404189, 2014).
breast cancer (66 papers, 2005 to 2025). A primary or metastatic malignant neoplasm involving the breast. "The activation of the PDGFR and ABL1 pathways is associated with long-term estrogen deprivation in MCF7 breast cancer cells and decreased anti-proliferative response to AI treatment in primary ER-positive breast carcinomas." (PMID 27911271, 2017). "Several proteins involved in this pathway are associated with breast cancer prognosis (including ERCC6 and POSTN34,35) and/or sensitivity/resistance to endocrine or other chemotherapy (including EGFR, ABL1, GNA13, and PTK736–39)." (PMID 39030258, 2024). "ABL1 is involved in the occurrence and development of several types of cancers including colon, kidney, and breast cancer." (PMID 38137334, 2023). "In previous studies, alterations in the Abl1 signaling in breast cancer cells led to increased chemoresistance while reducing proliferation." (PMID 33972619, 2021). "Single knockdown of either ABL1 or ABL2 in triple-negative breast cancer cells impaired anchorage independent growth, while expression of a constitutively active form of ABL1 in 4TI murine mammary tumors inhibited tumor growth." (PMID 34022881, 2021). "It has also been shown that activation of ABL kinases can promote breast cancer cell invasion, and treatment of cells with the ABL1 kinase inhibitor, imatinib, markedly inhibits cell motility." (PMID 29438361, 2018). "Ras signaling pathway is the pathway which ABL1 and ABL2 belong to and it is known that Ras signaling pathway activation is implicated in breast cancer invasion and growth." (PMID 28361687, 2017). "As a ubiquitously expressed non-receptor tyrosine kinase, ABL1 has been reported to be associated with glioblastoma and breast cancer." (PMID 32850446, 2020). "Moreover, RAC1, CDC42, MYL9, MYLK, ABL1, and other genes have been proved to be related to the progress of human breast cancer." (PMID 33306680, 2020). "Activated ABL1 kinase promotes invasion of breast cancer cells." (PMID 17280605, 2007). "While the effects of ABL1 or ABL2 inhibition has mixed effects on primary breast tumor growth, genetic or pharmacologic inhibition of the kinases impairs breast cancer metastasis." (PMID 34022881, 2021). "We next sought to determine a connection between mRNA expression levels of ABL1, ABL2, and CTTN in breast tumors to overall survival (OS) and disease-free survival (DFS) of breast cancer patients." (PMID 29774130, 2018). "Among the IgSF neighbor genes, ABL1 and PDGFR are well known breast cancer driver genes that promote acquired resistance to aromatase inhibitor (AI) therapy in ER+ breast cancers." (PMID 27911271, 2017). "The authors evaluated the result of single- or double-knockdown of ABL1 and ABL2 in breast cancer cells using RNA-seq analysis to reveal the signaling pathways required for ABL kinases-dependent bone metastasis." (PMID 28361687, 2017). "Abl kinases were first identified as oncogenes in leukemias, but recent reports have demonstrated a functional role for ABL1 and/or ABL2 in solid tumors including breast carcinoma, kidney cancer and melanoma." (PMID 25946048, 2015). "ABL1, a non-receptor tyrosine kinase, mainly exerts a key role in the development of solid tumors, including ovarian cancer, breast cancer, and lung cancer." (PMID 35898453, 2022). "We reviewed the functional properties of the driver nodes found to have the highest impact in controlling the essential proteins; they are ERBB2, SRC, PDPK1, PRKDC, mTOR for breast cancer, ERBB2, AKT1, GSK3B, ABL1 in pancreatic cancer, and RET in ovarian cancer." (PMID 28871116, 2017).
breast cancer (continued). "Activation of ABL1 kinase in NSCLC and breast cancer malignancies has been shown to occur downstream of the EGFR, human epidermal growth factor receptor 2 (HER2), and IGFR, as a late occurring event that contributes to the aggressive growth and metastasis of these solid tumors." (PMID 27086914, 2016). "In addition, low ABL1 expression had a negative impact on survival of patients with small cell lung carcinoma, ovarian carcinoma, and breast carcinoma." (PMID 36959186, 2023). "ABL1, a non-receptor tyrosine kinase, has been implicated in response to DNA-damaging chemotherapeutics in tissue culture, while high expression of the centrosomal protein CENPF has been associated with good chemoresponses in breast cancers." (PMID 32734521, 2020). "Notably, a recent report also mentioned that loss of function of ABL1 and/or ABL2 does not inhibit breast cancer metastasis to the lung, which further demonstrated that ABL does not play crucial roles in the anti-metastatic function of Ponatinib." (PMID 29667003, 2019). "The correlation between an increase in ABL1 and ABL2 protein levels, which is not accompanied by a similar association in distant metastasis free survival (DMFS) suggests contrasting roles for the two kinases in promoting breast cancer metastasis." (PMID 29774130, 2018).
gastrointestinal stromal tumor (48 papers, 2005 to 2025). "Beyond BCR::ABL1 mutations, genetic alterations have been critically evaluated for their role in conferring Imatinib resistance, especially in cancers like gastrointestinal stromal tumors (GISTs), where mutations in the KIT or PDGFRA genes are prevalent." (PMID 38607055, 2024). "In contrast, RB1 that was regarded as a tumor suppressor gene in gastrointestinal stromal tumors and was identified as a monotonically increasing gene, while three oncogenes including NFE2L2, ABL1, and LASP1 were identified as monotonically decreasing genes." (PMID 33273919, 2020).
polycythemia vera (48 papers, 2009 to 2025). "While CML and BCR::ABL1-negative MPN have been considered to be mutually exclusive, the WHO classification requires the exclusion of the BCR::ABL1 fusion in all cases of suspected MPN that cannot be clinically classified as Polycythemia vera." (PMID 40906032, 2025). "Nevertheless, it remains a viable therapeutic option in BCR:ABL1 negative MPNs, especially in polycythemia vera (PV) and essential thrombocytosis (ET)." (PMID 41228273, 2025). "As well known among hematologists, patients with one of the BCR/ABL-1-Philadelphia chromosome-negative MPNs, i.e., essential thrombocytosis (ET), polycythemia vera (PV) or primary myelofibrosis (PMF), have high incidences of CV-disease (CVD)." (PMID 36654555, 2022).